MEIS1 (Meis homeobox 1)
Diseases named in the same sentence as MEIS1 in open-access papers (continued):
Sharing a sentence is not in itself a finding about the gene and the disease.
leukemia (continued). "Furthermore, depletion of either of the Drosophila orthologs of MEIS1 or the PXB family, hth or exd, respectively, had previously been shown to rescue a HOXA9-NUP98 leukemia model in the Drosophila eye." (PMID 37720104, 2023). "MEIS1 is dysregulated in a large subset of acute myeloid leukemia (AML) patients through as yet undefined mechanisms and is critical for the maintenance of leukemia stem cells." (PMID 35624144, 2022). "We further validated Meis1 binding to the mouse Fli1 locus via ChIP-seq in two independent leukemia models, derived from lineage depleted bone marrow cells retrovirally transduced with NUP98-HOXD13/Meis1 (ND13/Meis1) and NUP98-HOXA10 homeodomain/Meis1 (NA10HD/Meis1)." (PMID 35624144, 2022). "Among the TFs that we and others identified to be selectively essential and overexpressed in KMT2A-rearranged leukemia, MEF2C, RUNX2, and MEIS1 are well-established direct targets of KMT2A fusion oncoproteins, prompting us to consider that one of these TFs drives IRF8 overexpression." (PMID 35301220, 2022). "Another study showed that in mixed lineage leukaemia (MLL)-rearranged leukaemia, miR-196b could directly target left HOXA9/MEIS1 oncogenes and FAS tumor suppressor." (PMID 33611311, 2021). "Sox4 deletion also delayed the onset of HOXA9/MEIS1-induced leukemia, although it did not affect MLL-AF10-induced leukemia." (PMID 34310280, 2021). "DOT1L is a therapeutic target for MLL-r leukemia: genome-wide hypermethylation of H3K79 is characteristic to the cancer 24 and DOT1L's catalytic activity is required for expression of MLL-target genes, such as HoxA9 and Meis1." (PMID 34373735, 2021). "USF2 depletion selectively downregulated HOXA9 expression in MLLr leukemia cells and impaired cell growth, which could be rescued by ectopic expression of HOXA9 and its partner MEIS1." (PMID 33001025, 2020). "Compared to levels in Hoxa9/Meis1 leukemias, endogenous Hoxa9 and Hoxa10 were considerably elevated in SQSTM1-NUP214 leukemias, whereas the levels of Hoxa3, Hoxa5, Hoxa7, Hoxa11 and Meis1 were comparable in Hoxa9/Meis1 and SQSTM1-NUP214 leukemias." (PMID 32343715, 2020). "However, expression of specific genes, such as HOXA9 and MEIS1, is strongly dependent on DOT1L specially in leukemias induced by MLL-fusion proteins." (PMID 33104701, 2020). "While Hoxa genes were upregulated in Mir142−/− GMPs, Meis1 and Pbx3 were not, consistent with the failure of these mice to develop leukemia." (PMID 33173219, 2020). "Ash1l, Ctnnb1, Hoxa7, and Hoxa9 were also upregulated in the single mutant Mir-142−/− GMPs compared to WT, but the key co-factors Meis1 and Pbx3 were not, potentially explaining why these mice failed to develop leukemia." (PMID 33173219, 2020). "The interaction between MEIS1 and HOXA9, for example, is known to be tumorigenic in leukemia." (PMID 32553107, 2020). "Contrary, overexpression of HOX family members (A5, A6, A7, A9, A10, B2, B5, and B7), including genes encoding TALE proteins (MEIS1; PBX3), and histone proteins was shared by all non-APL leukemias." (PMID 31467542, 2019). "They reported that combination of EPZ004777 and MI-2-2 (an inhibitor of MLL–Menin interaction) enhanced the down-regulation of important leukemia genes (i.e., MYC, HOXA9, and MEIS1) and anti-proliferative effects against MLL-r leukemia cells, compared to either single-agent treatment." (PMID 31157223, 2019). "In vivo, the presence of Hoxa9 expressed alone in murine bone marrow cells is not sufficient to rapidly induce leukemia (>6 months) whereas concomitant expression of Hoxa9 with Meis1 greatly shortened this period (approximately 67 days)." (PMID 31213012, 2019). "One of such peptidomimetic, MM-102, effectively decreases the expression of HOXA9 and Meis-1, two critical MLL/WDR5 target genes in MLL fusion protein-driven leukemogenesis, and specifically induces growth inhibition and apoptosis in leukemia cells harboring MLL fusion proteins." (PMID 30488017, 2018).
leukemia (continued). "Highly potent and selective antagonists of such interactions have been shown to effectively disrupt the MLL1 complex with WDR5, and Menin and decrease the expression of HoxA9 and Meis‐1, inhibiting proliferation and inducing hematopoietic differentiation in MLL1 leukemia cells." (PMID 28160335, 2017). "In contrast, leukemia-initiating cells lacking mitochondrial Fh1 efficiently propagated Meis1/Hoxa9-driven leukemia." (PMID 28202494, 2017). "Next, we examined whether LSD1 inhibition can block the expression of HoxA9 and Meis1, whose overexpression has been observed in MLL-rearranged leukemia." (PMID 26970896, 2016). "Our results indicate that, in the absence of mixed lineage leukemia fusions, an alternative pathway for engaging an oncogenic MEIS1-dependent transcriptional program can be mediated by DNMT3A mutations." (PMID 26434589, 2016). "Therefore, we analyzed the expression of the HOXA gene cluster, its co-factor MEIS1 and BMI1, all known to be deregulated in CALM/AF10-positive leukemias." (PMID 27588395, 2016). "HOXB7 and HOXD8 are new partners of MEIS1 that have never been reported to have leukemia-inducing potential prior to this study." (PMID 26606454, 2015). "In addition, Meis1 regulates the differentiation arrest, cycling activity and self-renewal of MLL leukemia cells, a critical rate-limiting determinant for establishing leukemia stem cell potential." (PMID 24498346, 2014). "Next, we tested whether SYC-522 inhibited the expression of MLL-fusion target genes HOXA9 and MEIS1, both of which have been found to be overexpressed in MLL-rearranged leukemia and downregulated by treatment with a DOT1L inhibitor." (PMID 24858818, 2014). "Furthermore, deletion of Bcl-2 delayed the onset and reduced the severity of HoxA9/Meis1 and MLL-AF9 leukemias." (PMID 24177192, 2013). "In that we observed dissimilar MEIS1, MEIS2, and PREP1 expression levels, we wished to confirm whether these changes were also observed in samples of patients with leukemia." (PMID 22185299, 2011). "MEIS1 quantitatively regulates the differentiation arrest, cycling activity, in vivo progression, and self-renewal of MLL leukemia cells, thereby functioning as a critical and rate-limiting determinant of leukemia stem cell potential." (PMID 19549311, 2009). "Analysis of the selected Hox A cluster and Hox cofactor genes revealed a high degree of co-expression between these in leukemia samples, where correlation coefficient between HOXA5, HOXA7, HOXA9 and MEIS1 ranged between 0.83 and 0.92 (Spearman rank correlation, p<0.0001 in all cases)." (PMID 17712416, 2007). "Additional binding specificity and stability is in part achieved through interaction with other homeodomain-containing proteins from the multimember PBX or MEIS1 families and co-transduction of MEIS1 with Hox and NUP98-Hox genes also strongly accelerate the onset of leukemia in mice." (PMID 17712416, 2007). "In addition, some other leukemias overexpressing HOX and MEIS1 genes might respond to menin inhibition such as leukemias with rearrangement of the nucleoporin 98 gene (NUP98)." (PMID 38651453, 2024). "By driving expression of genes such as the Hox genes and Meis1, MLL-fusions confer cells with stem cell-like properties, including acquisition of self-renewal capacity in otherwise short-lived lineage-committed HPCs which can then function as potent leukemia stem cells (LSCs)." (PMID 35350382, 2022). "Hypoxia or HLF increased the OS, rescuing leukemia progression in Meis1-lacking cells." (PMID 36139768, 2022). "The presence or absence of PREP1 has not yet been taken into account in the case of MLL-r, Mixed Lineage Leukemia, a leukemia due to translocation of several genes to the amino terminus of the MLL gene, which appears to be mainly dependent on the overexpression of MEIS1." (PMID 34698191, 2021).
leukemia (continued). "Therefore, inhibition of DOT1L by SYC-522 treatment shows that reducing DOT1L methyltransferase activity and its downstream targets MEIS1 and HOXA9, can promote differentiation and might represent a valuable approach for treating MLL-rearranged leukemia." (PMID 34698191, 2021). "However, Meis1 alone does not induce leukemia, Meis1 as an accelerator of Hoxa9-induced leukemia but not stricto sensu as an oncogene." (PMID 31213012, 2019). "MEIS1, which is known as a key regulator in transcriptional regulation, cellular differentiation, and cell-cycle control, exhibited significant increases in both MLL fusion protein binding and mRNA expression on MLL-ENL activation in MLL-ENL leukemia cases and in an inducible cellular model." (PMID 31523525, 2019). "MEIS1 expression was also variable in a pediatric MLL-rearranged ALL patient dataset, highlighting the existence of a previously undescribed metabolic variability in MLL-rearranged leukemia that may contribute to the heterogeneity of the disease." (PMID 30670779, 2019). "Thus, mitochondrial Fh1 is necessary for efficient LIC generation but is not required for their ability to efficiently propagate Meis1/Hoxa9-driven leukemia." (PMID 28202494, 2017). "As previously reported, MEIS1 alone did not induce leukemia." (PMID 26606454, 2015). "Meis1 cooperates with HoxA9 in leukemogenesis, as its overexpression accelerates the emergence of HoxA9-induced acute myeloid leukemia, whereas Prep1 overexpression does not accelerate HoxA9-induced leukemia but rather delays its onset." (PMID 26285139, 2015). "Furthermore, AF4-MLL is able to induce leukemias in mice without activating HOXA or MEIS1 expression." (PMID 23352661, 2013). "Therefore, it could be important to evaluate MEIS1 and PREP1 expression in patients with leukemia prior to and after chemotherapeutic treatment and to correlate these findings with the clinical response." (PMID 22185299, 2011). "The integration was initially tested on a leukaemia dataset, highlighting interesting imbalanced regions containing genes involved in ALL pathology: 1) MLL region on chromosome 11; 2) the region containing HOX gene cluster on chromosome 7; and 3) the region containing MEIS1 on chromosome 2." (PMID 21481242, 2011). "Further, our data showed a dampening effect of SMAD1 presence combined with TGF-β stimulation on the expression of the two KMT2A-rearranged leukemia-driving genes HOXA9 and MEIS1, which has not been described in literature yet." (PMID 39834944, 2024). "As a result of small-molecule library screening, it was observed that small-molecule CCI-007, although not specific for MEIS1, had a cytotoxic effect within few hours in CALM-AF10, MLL-r, and SET-NUP214 leukemia cell lines." (PMID 33402862, 2020). "Thus, MLL fusion proteins might promote leukemogenesis not only by HOXA9 and MEIS1 upregulation, but also by keeping the ZNF521 overexpressed, which in turn contributes to a block of differentiation or to the maintenance of an undifferentiated state of leukemia cells." (PMID 28412727, 2017). "All the MYC/HOXA9- and HOXA9/MEIS1-induced leukemias were positive to a myeloid marker Mac1 but negative to lymphoid marker B220 or CD3e, indicating that both MYC/HOXA9- and HOXA9/MEIS1-combinations induced myeloid leukemia." (PMID 34310280, 2021). "Notably, after treating MV4;11 cells with 100 nM inhibitor for 7 days we observed no discernable effect on the expression of HOXA9 and MEIS1, despite the emphasis on these genes as the critical mediators of DOT1L’s effects in MLL-r leukemia." (PMID 34263728, 2021). "However, their expression did not correlate with HOXA5, HOXA7, HOXA9 or MEIS1 and only weakly with PBX3 expression in human leukemia (Spearman, r = 0.37, p = 0.033 and r = 0.44, p = 0.078 respectively)." (PMID 17712416, 2007).
acute myeloid leukemia (56 papers, 2009 to 2026). Acute myeloid leukemia (AML) is a group of neoplasms arising from precursor cells committed to the myeloid cell-line differentiation. "In particular, MEIS1 overexpression is very often observed in acute myeloid leukemia and is associated with poor prognosis." (PMID 33733070, 2021). "Myeloid ecotropic viral integration site 1 (MEIS1) protein plays a synergistic causative role in acute myeloid leukemia (AML)." (PMID 28270206, 2017). "Meis1 has been implicated in the pathogenesis of various cancers, with historical observations linking its overexpression to both acute lymphoblastic leukemia and acute myeloid leukemia (Meriç and Kocabas, 2022)." (PMID 39758840, 2024). "Although HOXA9 and MEIS1 play synergistic and pathogenic roles in acute myeloid leukemia (AML), both molecules are considered difficult to drug due to the lack of deep pockets for binding SMIs." (PMID 37496997, 2023). "Overexpression of the Hox and Meis1 genes triggers leukemogenesis, is associated with high-risk acute myeloid leukemia (AML) and currently cannot be targeted by drugs." (PMID 28399410, 2017). "Meis1 is also associated with leukemogenesis in humans with a frequent up-regulation in primary acute myeloid leukemia (AML) and acute lymphoblastic leukemia (ALL) samples." (PMID 26221532, 2015). "The expression level of MEIS1 in acute myeloid leukemia (AML) is negatively correlated with prognosis." (PMID 34368227, 2021). "Hoxa9 is critical for the development and self-renewal of healthy HSCs, but its ectopic co-expression with Meis1 in haematopoietic stem and progenitor cells leads to rapid acute myeloid leukaemia (AML) onset in mice." (PMID 33674652, 2021). "HOXA9 and MEIS1 are frequently upregulated in acute myeloid leukemia (AML), including those with MLL-rearrangement." (PMID 34502319, 2021). "MEIS1 is a key transcription factor orchestrating transcriptional programs for the maintenance of CSC plasticity in acute myeloid leukemia (AML)." (PMID 33453053, 2021). "MEIS1 is upregulated in many human cancers, including the majority of acute myeloid leukemias (AML), whereas PREP1 has tumor-suppressive properties." (PMID 33768097, 2021). "Our analysis highlighted Meis1 and Hoxa9 as two factors with established roles of blocking myeloid differentiation, most notably in the context of acute myeloid leukaemia cells." (PMID 33103827, 2020). "Conversely, AP-2α activated Hoxa7/9 and the Hox cofactor Meis1 to enhance the proliferation and cell survival of acute myeloid leukemia (AML) cells." (PMID 31534499, 2019). "Syk inhibition disrupts the regulatory loop and prolongs survival of mice with Hoxa9/Meis1-driven acute myeloid leukemia." (PMID 28399410, 2017). "Consistent with this conclusion, elevated Meis1 expression has also been observed in several tumor types including acute myeloid leukemia, lung adenocarcinoma tumors, neuroblastomas, ovarian carcinomas, and nephroblastomas." (PMID 25013928, 2014). "Even though many studies support a tumor suppressive function for miR-499a-5p in different human tumors such as osteosarcoma, cervical cancer, acute myeloid leukemia and glioma, our data reveal a pro-proliferative role possibly through modulating Meis1 mRNA and protein expression." (PMID 39851553, 2025). "Dysregulation of KMT2 proteins (MLL) and MEIS1 contribute to acute myeloid leukemia (AML)." (PMID 40021842, 2025). "Additionally, in acute myeloid leukemia, the activity of Meis1 has been shown to be dependent on the activation of the Wnt/β-catenin signaling pathway." (PMID 39851553, 2025). "Since KMT2A‐r acute myeloid leukemia (KMT2A‐r‐AML) is characterized by the overexpression of HOXA/MEIS1/PBX3 homeobox genes, tackling the interactions of MEIS1/PBX3 may offer a promising therapeutic approach for treating these AML subtypes." (PMID 39428967, 2024). "Indeed, co-expression of MEIS1 with HoxA9 can induce growth factor-dependent oligoclonal acute myeloid leukemia in less than three months in mice." (PMID 34698191, 2021).
acute myeloid leukemia (continued). "Meis1 was upregulated in acute myeloid leukemia and glioblastoma." (PMID 33402862, 2020). "Moreover, MEIS1 is essential for the expression of genes driven by the HOXA9-NUP98 fusion in acute myeloid leukemia." (PMID 32681068, 2020). "In acute myeloid leukemia, overexpression of MEIS1 has been consistently observed." (PMID 30496486, 2019). "For example, aberrant expression of MEIS-1 promoted the development of acute myeloid leukemia." (PMID 29632641, 2018). "Researchers have examined the role of HOX genes (HOXA9 and HOXB3) and MEIS1 in the pathogenesis of acute myeloid leukemia (AML) in murine models." (PMID 41226583, 2025). "The interaction of menin with KMT2A protein is considered responsible for the leukemogenesis in acute myeloid leukemia (AML) through the upregulation of the HOX/MEIS1 genes." (PMID 39594904, 2024). "Indeed, MEIS1 forms complexes with HOXA9 in acute myeloid leukemia to drive carcinogenesis." (PMID 35743243, 2022). "Myeloid ecotropic virus insertion site 1 (MEIS1) is essential for normal hematopoiesis and is a critical factor in the pathogenesis of a large subset of acute myeloid leukemia (AML)." (PMID 35624144, 2022). "Meis1 expression is frequently up-regulated in primary acute myeloid leukemia (AML) and acute lymphoblastic leukemia (ALL)." (PMID 25013928, 2014). "The inhibitors suppressed expression of MLL target genes HoxA9, Meis1 and Myc, and selectively inhibited proliferation of MLL-r and other acute myeloid leukemia cells with EC50 values as low as 4.7 μM." (PMID 37958457, 2023). "Interestingly, Meis1 is overexpressed in lymphoid neoplasm diffuse large B-cell lymphoma, cholangiocarcinoma, kidney renal clear cell carcinoma, ovarian serous cystadenocarcinoma, glioblastoma multiforme, acute myeloid leukemia, brain lower grade glioma, and thymoma." (PMID 33402862, 2020). "Additionally, in acute myeloid leukemia (AML), WBP5 overexpression has been associated with poor prognosis, correlating with increased expression of HOX gene cluster (HOXA5, HOXA7, HOXA9, and HOXA10), MEIS1, and FOXC1." (PMID 40002180, 2025). "Xinyue Zhou and Rui Lu discovered that SCUBE1 involving in the initiation and maintenance of MLL-rearranged (MLL-r) acute myeloid leukemia is a novel transcriptional target of HOXA9 and MEIS1, understanding the role of SCUBE1 is contributed to clarify the mechanism of HOXA9/MEIS1in human diseases." (PMID 36376832, 2022). "Chromosomal translocations in some acute myeloid leukemia (AML) cases produce a fusion gene known as ZMYND11-MBTD1 (ZM), which recruits TIP60/KAT5 to stemness-related gene regions, including MYC, HoxA, Meis1, and Sox4." (PMID 41227365, 2025). "Acute myeloid leukemia (AML) with NPM1m—which accounts for approximately 30% of AML cases and AML or acute lymphoblastic leukemia (ALL) with KMT2Ar—and is present in 5–10% of cases, shares a common pathogenetic mechanism: the aberrant activation of the MEIS1–HOXA axis." (PMID 40710017, 2025). "Indeed, Meis1 aberrant expression actively contributes to acute myeloid leukemia, whereas Fut8 overexpression has been found in non-hematopoietic cancer." (PMID 33733070, 2021). "In hematological malignancies, TRIB2 as a target gene of MEIS1, E2F1, and NOTCH1 participates in acute myeloid leukemia (AML) and T cell acute lymphoblastic leukemia (T-ALL)." (PMID 33794905, 2021). "However, HoxA9 selective collaboration with Meis1, but not with Prep1, drastically lowers the latency of acute myeloid leukemia (AML) onset in mice." (PMID 24809472, 2014). "For instance, TET1 has been considered as a critical oncogenic epigenetic regulator in acute myeloid leukemia (AML), which plays its role by promoting the expression of oncogenic targets, including HOXA9, MEIS1 and PBX3, and suppressing the expression of tumor suppressor miR-22." (PMID 34957093, 2021).